GPD1 (glycerol-3-phosphate dehydrogenase 1)
Diseases named in the same sentence as GPD1 in open-access papers (continued):
Sharing a sentence is not in itself a finding about the gene and the disease.
tumor (23 papers, 2017 to 2025). "This study reveals a new mechanism underlying the tumor suppression ability of GPD1 and provides a new perspective on forming composite prognostic biomarkers with GPD1 and lipid metabolites." (PMID 37483742, 2023). "One of the variants highlighted in our research (GPD1:c.548C>T) has a high clonality ratio and may be associated with the loss of function of GPD1 at the beginning of tumor formation, thus leading to cancer aggressiveness." (PMID 39684297, 2024). "The GPD1 maybe act as a tumor-suppressor gene and be used for the early diagnostic or prognostic biomarkers." (PMID 37483742, 2023). "Like PFKM and GPD1, PKLR also has a variant with a VAF above 0.5, indicating a potential relationship with the initial stages of tumor formation and possible glycolytic dysfunction." (PMID 39684297, 2024). "It should also be mentioned that some reports have suggested that GPD1 plays a tumor-promoting role." (PMID 38689091, 2024). "The downstream effects of increased G3P include different mechanisms for the tumor-promoting and tumor-suppressing activities of GPD1." (PMID 38689091, 2024). "We suggest that future studies should include longitudinal analyses of tumor tissue with these variants (in GPD1, PLKR, and PFKM) to understand their clonal evolution and the possible action as tumor driver progression." (PMID 39684297, 2024). "GPD1 is considered an anti-tumor gene, and its overexpression inhibits proliferation, migration, and invasion." (PMID 39684297, 2024). "Supporting this is that the roles of each GPD are mostly opposite in cancer, with GPD1 generally acting as a tumor suppressor and GPD2 acting as a tumor promoter." (PMID 38689091, 2024). "GPD1 has been detected in tumor cells of various tumor types and is involved in the generation of glycerol within an active glycolysis pathway that is a hallmark of neoplastic cells." (PMID 38275375, 2023). "We found that the GPD1 expression levels had an obvious decrease at 1.51 (median) in the tumor group compared with the normal group at 192.53 (median, p < 0.001)." (PMID 37483742, 2023). "The result showed that the GPD1 expression level was significantly downregulated in the tumor tissues compared with the normal tissues (p < 0.001)." (PMID 37483742, 2023). "Upregulation of G3P levels, an intracellular GPD1 catalytic product, has been found to inhibit tumor cell proliferation in vitro." (PMID 35836291, 2022). "Compared with the control group, the GPD1 overexpression group had significantly reduced tumor weight." (PMID 35836291, 2022). "We proposed a new candidate called Gpd1, which was reported to inhibit the proliferation of tumor cells." (PMID 36275896, 2022). "Based on transcriptomics and metabolomics, GPD1 promotes Ca2+ influx and apoptosis of tumor cells via the lysoPC-PAFR-TRPV2 axis." (PMID 35836291, 2022). "It has been demonstrated that GPD1 exhibits extremely low expression levels or absence in some tumor tissues." (PMID 35836291, 2022). "We detected the expression of GPD1 in 4 pair normal and tumor tissues by western blotting, and the results showed that GPD1 expression was also significantly reduced in tumor tissue." (PMID 35836291, 2022). "As such, we tested the effect of Caki1 and 769P cell lines that stably expressed GPD1 in a murine xenograft model on tumor growth as compared to vector control cell lines." (PMID 34098990, 2021). "In this study, we discovered that HIF1α can positively regulate GPD1 at the transcriptional level to suppress tumor progression via inhibiting mitochondrial function and lipid metabolism." (PMID 34098990, 2021). "Tumor growth was significantly inhibited by the overexpression of GPD1, and the tumors in the GPD1-overexpressing groups also had smaller sizes and lower weights than those in the control groups." (PMID 34098990, 2021).
tumor (continued). "We examined the expression of GPD1 in renal tubular epithelial cells (HK2) and various renal ccRCC cell lines and found that GPD1 was generally expressed at a lower level in tumor cell lines." (PMID 34098990, 2021). "The NUP85, HAX1, GNPDA1 and HDLBP protein levels were significantly elevated in tumor tissues compared to normal samples, while GPD1 was significantly down-regulated in tumor tissues." (PMID 33663535, 2021). "Our results, therefore, suggest a novel tumour suppressor function for GPD1 and contribute to the understanding of cancer metabolism." (PMID 29254166, 2017). "With more clinical studies showing lower GPD1 in cancer tissues, it seems that the tumor-promoting mechanism of GPD1 may operate in particular contexts." (PMID 38689091, 2024). "As many studies have demonstrated the low expression of GPD1 in various types of cancer and have suggested that it is a tumor suppressor, most of the mechanistic studies have investigated the effects of GPD1 overexpression on cancer cell proliferation and growth." (PMID 38689091, 2024). "Glycerol 3-phosphate dehydrogenase 1 (GPD1) acts as a tumor suppressor in various types of cancer." (PMID 37483742, 2023). "GPD1+ GSCs were enriched at tumor borders and shown to drive tumor relapse after chemotherapy." (PMID 35920986, 2022). "In contrasts, increased tumor levels of GPD1 positively correlated with better OS and DFS of the patients, suggesting that preservation of the shuttling of electrons to mitochondria could favor patients’ prognosis." (PMID 35534478, 2022). "To further determine that the suppression of tumor growth by GPD1 is dependent on its catalytic activity, which can promote the accumulation of G3P and NAD+, we next constructed 5637 and T24 cells overexpressing the GPD1 mutant (K120A variant)." (PMID 35836291, 2022). "Transwell migration and tumor sphere formation assays indicated that the migration and sphere-forming capacities of 5637 and T24 cells were also suppressed by overexpression of GPD1." (PMID 35836291, 2022). "To further determine whether GPD1 promotes tumor cell apoptosis via TRPV2-mediated Ca2+ influx, we silenced the expression of TRPV2 with siRNA." (PMID 35836291, 2022). "Therefore, the applicability of GPD1 as a target in different tumor types needs to be further investigated." (PMID 35836291, 2022). "Based on these results, we were interested in the role of GPD1 in tumor growth in vivo." (PMID 34098990, 2021). "We found that GPD1 protein was mainly expressed in the cytoplasm of renal tubular epithelial cells, and the expression level in benign tissues was much higher than that in tumor tissues." (PMID 34098990, 2021). "In addition to these lipid metabolic changes, decreased cell proliferation, migration, and invasion, as well as the inhibition of xenografted tumor growth, were also observed, consistent with the correlation between high GPD1 protein levels and better ccRCC patient survival." (PMID 38689091, 2024). "The exact extent of these GPD1 tumor-promoting roles and the context may require further studies." (PMID 38689091, 2024). "Highlighting the anti-correlation of GPD1 and GPD2 in cancer, a recent study showed that GPD1 has tumor-promoting effects and that GPD2 has tumor-suppressing effects." (PMID 38689091, 2024). "Consistently, the GPD1 expression was found to be positively correlated with M2, TfH, and CAF infiltration levels using the Tumor IMmune Estimation Resource (TIMER2.0) algorithm." (PMID 35563509, 2022). "Our data showed that lysoPC converted from the GPD1 catalytic product G3P induced TRPV2 expression via PAFR to promote Ca2+ influx, which led to apoptosis of tumor cells." (PMID 35836291, 2022). "In addition, based on the role of GPD1 in tumor proliferation and migration, it is possible to find a drug that binds the enzyme receptor at its binding site and promotes the expression of GPD1, which could provide a novel therapy for ccRCC, but this requires further study." (PMID 34098990, 2021).
tumor (continued). "ENO3, FBP1, FBP2, GPD1, and ALDOB were all glycolytic pathway-related proteins with inhibitory effects on tumor." (PMID 33200655, 2020). "For example, a significantly higher GPD1 level was found in dormant brain tumor stem cells than in normal neuronal stem cells, which can contribute to differences in glycerophospholipid (GPL) metabolism and tumor relapse after chemotherapy." (PMID 38689091, 2024). "For GPD1, no inhibitor studies have been reported, probably because it is known for its tumor-suppressive activity." (PMID 38689091, 2024). "Nevertheless, as in the GPD1 case, there can be some specific contexts where GPD2 may have tumor-suppressive roles, and the extent of these effects should be addressed in future studies." (PMID 38689091, 2024). "However, GPD1 KO increased the sensitivity of cancer cells to the antiproliferative effects of ETC inhibitors and suppressed xenograft tumor growth under ETC inhibition, indicating that GPD1 promoted tumor growth." (PMID 38689091, 2024). "Fatty acid binding protein 4 (FABP4) and glycerol-3-phosphate dehydrogenase 1 (GPD1) separate SR cells from those in other organs through principal component 2, likely due to tissue-specific differences in cellular proteomes, function, and interactions between SR cells and their tumor environment." (PMID 39910169, 2025). "Additionally, it would be interesting to determine whether patients with high GPD1 and/or GPD2 levels in their tumor tissues might respond better to metformin treatment." (PMID 38689091, 2024). "Notably, the increase in G3P induced by GPD1 overexpression (OE) was not statistically significant, but GPD1 OE alone, without metformin, reduced in vivo tumor xenograft growth and mitochondrial oxygen consumption." (PMID 38689091, 2024). "In addition, NUP85, HAX1, GNPDA1 and HDLBP exhibited elevated mRNA expression levels in GI tumor tissues when compared to the adjacent non-tumor tissues, whereas GPD1 expression was suppressed in GI tumor tissues compared to the non-tumor tissues." (PMID 33663535, 2021).
cancer (20 papers, 2013 to 2026). A tumor composed of atypical neoplastic, often pleomorphic cells that invade other tissues. "High GPD1 expression with high pro-tumorigenic immune cells (M2 macrophage, and cancer associated fibroblast) had worst survival." (PMID 35563509, 2022). "A high expression of GPD1 with high M2 macrophage (M2, pro-tumorigenic) as well as high cancer associated fibroblast (CAF) led to the worst survival." (PMID 35563509, 2022). "Regarding the downstream mechanisms by which GPD1 regulates cancer growth, two studies proposed the common involvement of the reaction product G3P in different contexts." (PMID 38689091, 2024). "GPD1 emerges as a regulator of stem cell exosome secretion, impacting various cancers such as renal clear cell carcinoma, bladder, prostate, breast, and epithelial ovarian cancer." (PMID 38898093, 2024). "In summary, we identified and validated a glycolysis associated five-gene risk signature (NUP85, GPD1, HAX1, GNPDA1 and HDLBP) that can predict the OS of GI Asian cancer patients." (PMID 33663535, 2021). "Increased glycolysis in cancer cells ensures the availability of dihydroxyacetone phosphate (DHAP) for conversion by glycerol-3-phosphate dehydrogenase 1 (GPD1) to glycerol-3-phosphate and thence phospholipids for cell membrane synthesis." (PMID 34631530, 2021). "The median level of GPD1 mRNA expression was also significantly lower in the cancer tissues than in the adjacent normal tissues (p < 0.001)." (PMID 29254166, 2017). "Kaplan-Meier analysis curves of the TCGA cohort were further applied in the 11 cancer types that exhibited reduced GPD1 mRNA expression level." (PMID 29254166, 2017). "We also included the deletion mutants for an additional five yeast genes (HRK1, TPO3, MET7, PNP1 and GPD1), which are HP and whose products are orthologous to specific cancer-drug targets." (PMID 23531409, 2013). "GPD1 usually stops cancer cell growth, while GPD2 often encourages it." (PMID 38689091, 2024). "Moreover, GPD1 OE promoted the activation of GPS to rescue cancer cell proliferation under CI inhibition, demonstrating that GPS can compensate for mitochondrial dysfunction in ATP production and redox homeostasis." (PMID 38689091, 2024). "Our RNA-seq and metabolomics results suggest that GPD1 can regulate many cellular signaling pathways and metabolic pathways, but these pathways may differ between cancer types." (PMID 35836291, 2022). "The enzymes of glycolysis glyceraldehyde-3-phosphate dehydrogenase (GAPDH), enolase 1 (ENO1) and lactate dehydrogenase (LDHA) and glycerol-3-phosphate dehydrogenase (GPD1) which shuttles electrons to mitochondria, revealed a significant increase in carcinomas when compared to NAT." (PMID 35534478, 2022). "GPD1 protein was mainly observed both in the cytoplasm of cancer cells and the nucleus." (PMID 29254166, 2017). "Interestingly, Pld1 and Gpd1 have be reported to be critical for cancer progression and metastasis." (PMID 39512339, 2024). "Moreover, considering that several studies hint at a key role for human GPD1 in cancer metabolism, our findings highlight the need to better understand how this highly studied enzyme influences gene expression, cell growth and differentiation, and metabolic signaling networks." (PMID 35536221, 2022). "However, seven cancer types with GPD1 amplification also exhibited reduced GPD1 mRNA expression levels (p < 0.05), suggesting additional mechanisms may lead to reduced mRNA levels of GPD1." (PMID 29254166, 2017). "We found that the GPD1 copy number in the 21 human cancer types was different; it could be shallow deleted, unchanged (diploid) or gained, and 8 of the cancers exhibited deletion of GPD1 in more than 15% (38.1%, 8/21) of cases, while 2 exhibited deletion in more than 20% (9.52%, 2/21) of cases." (PMID 29254166, 2017).
cancer (continued). "Compared to other components of the bioenergetic machinery, e.g., the TCA cycle, glycolysis, and the ETC, much less is known about the roles of GPS or its components GPD1 and GPD2 in cancer." (PMID 38689091, 2024). "To date, numerous studies have explored the involvement and mechanisms of GPD1 and GPD2 in cancer and other diseases, encompassing reports of controversial and non-conventional mechanisms." (PMID 38689091, 2024). "Of the 10 proteins, the preceding text showed that some studies identified RRM2, PLOD2, MKI67, MCM5, and CKD1 promoted cancer progression and FBP1, FBP2, ENO3, GPD1, and ASS1 inhibited cancer progression, which was consistent with our results." (PMID 33200655, 2020). "In this review, we combined several critical studies on the roles of the GPS proteins GPD1 and GPD2 to summarize the current understanding of the metabolic and functional impacts of GPS, particularly focusing on their involvement in diseases such as cancer." (PMID 38689091, 2024). "Studies show that two types of GPDs, GPD1 and GPD2, can affect cancer growth differently." (PMID 38689091, 2024).
metabolic disease (4 papers, 2013 to 2025). A congenital disorder (due to inherited enzyme abnormality) or acquired (due to failure of a metabolically important organ) disorder resulting from an abnormal metabolic process. "Alterations in GPD1 are implicated in many metabolic disorders, and this enzyme is critical for cell health." (PMID 41207623, 2025). "As GPD1 generates G3P, which connects carbohydrate and lipid metabolism and is involved in NADH/NAD+ recycling, abnormal activity of GPD1 is expected to cause metabolic diseases." (PMID 38689091, 2024). "Therefore, abnormal expression of GPD1 may lead to metabolic diseases." (PMID 40631874, 2025).
infection (2 papers, 2017 to 2024). The state of being infected such as from the introduction of a foreign agent such as serum, vaccine, antigenic substance or organism. "GPD1, encoding GPD1 was downregulated in cord DCs already from 6 h of infection and stayed downregulated as the infection proceeded, while in adults it remained unchanged until 16 h, at which it was downregulated." (PMID 28993767, 2017).
autosomal recessive disease (1 paper, 2025). Autosomal recessive form of disease. "HTGTI is a rare autosomal-recessive disease caused by inactivating mutations in glycerol-3-phosphate dehydrogenase 1 (GPD1)." (PMID 40465020, 2025).
GI tumors (1 paper, 2021). "We found that GDP1 expression levels in GI tumors was relatively low, which may be related to GPD1 deficiency and its effect on gluconeogenesis." (PMID 33663535, 2021). "We identified five novel glycolysis-associated genes (NUP85, GPD1, HAX1, GNPDA1, and HDLBP) in GI tumor and normal tissues." (PMID 33663535, 2021). "Therefore, the role of GPD1 in GI tumors is worthy of attention." (PMID 33663535, 2021).
GPD1 also shares sentences with these, for which no sentence is quoted: Hepatic steatosis (3 papers); dyslipidemia (2); lung carcinoma (2); adenocarcinoma (1); Alzheimer disease (1); brain cancer (1); colorectal cancer (1); coronary artery disease (1); dyslipoproteinemic corneal dystrophy (1); Epithelial Ovarian Cancer (1); Failure to thrive (1); heart failure (1); hepatocellular carcinoma (1); Hepatomegaly (1); hyperferritinemia-cataract syndrome (1); Hyperglycemia (1); hyperlipoproteinemia type I (1); hypothyroidism (1); leukemia (1); lung squamous cell carcinoma (1); mevalonic aciduria (1); myopathy (1); neurodegenerative disease (1); ovarian serous cystadenocarcinoma (1); pancreatic adenocarcinoma (1); renal cell carcinoma (1); renal fibrosis (1); sarcoma (1); steatosis (1); tauopathies (1).
A further 2 diseases each share a sentence with GPD1 in 1 paper.